CRP (C-reactive protein)
Diseases named in the same sentence as CRP in open-access papers (continued):
Sharing a sentence is not in itself a finding about the gene and the disease.
cancer (continued). "Indeed, there is now good evidence that CRP and albumin alone and these indices have prognostic value in adult cancer populations." (PMID 34944774, 2021). "However, our study is the first to show that an abnormal PCT (>0.05 ng/ml) and elevated CRP (>1 mg% in whole cohort, >2.5 mg% in cancer cohort) predicts worse outcome." (PMID 34786866, 2021). "Inflammation has been widely recognized as a factor that contributes to cancer progression, and many inflammatory markers, such as C-reactive protein (CRP), the Glasgow Prognostic Score (GPS), and the modified GPS (mGPS), have been shown to be associated with survival in CRC patients." (PMID 34765598, 2021). "The concept of a functional relationship between inflammation and cancers has been stimulated and expanded by research on various systemic inflammatory biomarkers, such as CRP, the Glasgow Prognostic Score, cytokines, and leukocytes, which can be easily measured in clinical practice." (PMID 34943437, 2021). "We also examined the current implementation of opioid medications for cancer pain among groups according to CRP levels because opioids may be a confounding factor in the relationship between CRP levels and pain." (PMID 34223511, 2021). "Therefore, to the best of our knowledge, limited information is currently available on the relationship between elevated CRP levels and pain in patients with cancer cachexia." (PMID 34223511, 2021). "Biomarkers of the peripheral blood, such as the neutrophil‐to‐lymphocyte ratio (NLR) or the C‐reactive protein (CRP), have been associated with COVID‐19 disease severity in patients both with or without cancer." (PMID 34121360, 2021). "The combination of CRP and albumin into a score, termed as the GPS, is a widely accepted index to characterize systemic inflammation and is associated with the prognosis in advanced cancer disease." (PMID 33763364, 2021). "As an inflammatory marker, higher CRP may reflect acute inflammation which trigger for thromboembolism, or CRP itself is related to coagulation pathway and therefore may activate the cancer-specific prothrombotic mechanisms." (PMID 33549056, 2021). "Additionally, the CRP/albumin ratio, believed to be a predictor of overall survival in many cancers, was decreased during n-3 supplementation." (PMID 33801979, 2021). "Moreover, numerous studies have revealed associations of high levels of inflammatory markers, such as C-reactive protein (CRP) and IL6, with an increased risk of developing different types of cancer." (PMID 34685542, 2021). "Moreover, to definitively evaluate the prognostic and predictive value of CRP and IL-6, their concentrations should be analyzed with relation to the overall and cancer-specific survival rate." (PMID 34441316, 2021). "IL-6 induces the synthesis of CRP, a sensitive marker of cancer cachexia as well as inflammation." (PMID 33801569, 2021). "Two main hypotheses exist regarding CRP elevation in cancer pathogenesis; one hypothesis suggests that CRP elevation occurs secondary to the inflammation of tumor growth, whereas the second suggests that CRP elevation is caused by the tumor itself." (PMID 34512646, 2021). "Perioperative C‐reactive protein (CRP) levels have effects on the prognosis of cancer patients." (PMID 33270989, 2021). "Some researchers suggested that CRP/PAlb was more sensitive to CRP/Alb for cancer prognosis." (PMID 34603476, 2021). "Considering the criteria for an mGPS of 2 (CRP > 1.0 mg/dL and Alb < 3.5 g/dL), our results indicate that a high cut-off value for CRP (3.0 mg/dL) and a low cut-off value for Alb (2.5 g/dL) are estimates from advanced cancer patients near the end of life." (PMID 33757453, 2021). "Recent studies have demonstrated that several systemic inflammation biomarkers, such as neutrophil-lymphocyte ratio, C-reactive protein (CRP)-albumin ratio, platelet-lymphocyte ratio, were acting as predictors of prognosis in several types of malignant tumors, including CRC." (PMID 34436973, 2021).
cancer (continued). "Recently, inflammatory biomarkers, such as C-reactive protein (CRP), the neutrophil-to-lymphocyte ratio (NLR), the monocyte-to-lymphocyte ratio (MLR), and the platelet-to-lymphocyte ratio (PLR) were found to be associated with cancer prognosis." (PMID 33435255, 2021). "We hypothesized that the readily available, routinely measured biomarkers CRP and albumin may have prognostic value in older cancer patients." (PMID 34944774, 2021). "As a host response to cancer-mediated by cytokines, systemic inflammation often occurs with an activation of the hepatic acute-phase protein response, which can lead to increased levels of C-reactive protein (CRP) and decreased levels of albumin." (PMID 34830936, 2021). "The tumor microenvironment may also play a role in cancer pathogenesis and be reflected in CRP measurements." (PMID 34512646, 2021). "IMMUNEPOTENT CRP is a promising immunotherapy that induces regulated cell death in cancer cells." (PMID 33531687, 2021). "Increased PTX-3, PCT and CRP levels in the current study, inflammation may be one of the key promoters in the development and progression of cancer." (PMID 33776564, 2021). "Moreover, in cancer cachexia, inflammatory cytokines, such as IL-6 derived from cancer cells, act on hepatocytes to increase CRP production and increase protein catabolism." (PMID 33757453, 2021). "The ratio CRP/Alb is a prognostic indicator for several cancers." (PMID 34603476, 2021). "In our study, cross-comparing spleen and lymph node proteomic data led us to identify several common biomarkers of interest, among which C-reactive protein, which represents one member of the positive acute-phase response proteins commonly elevated in inflammatory diseases and cancers." (PMID 34445271, 2021). "Elevations in IL-6 and CRP correlate with cancer related anemia, and it has been postulated that states of persistent inflammation may induce a hypermetabolic state leading to malnutrition and cachexia." (PMID 34512646, 2021). "One study speculates that GPS shows inflammation status and nutritional status of cancer patients as a better predictor of prognosing cancer than CRP." (PMID 34720749, 2021). "Furthermore, the results showed that hs-CRP levels were significantly higher in late-stage cancer patients compared with those in early-stage in both chemotherapy regimens groups." (PMID 34711013, 2021). "Does killing the cancer or radiotherapy (RT)-induced inflammation change the CRP level?" (PMID 34926085, 2021). "Moreover, the modified Glasgow Prognostic Score (mGPS), consisting of albumin and C-reactive protein (CRP), has also shown to be prognostic for survival in cancer patients." (PMID 34148164, 2021). "Furthermore, in a random survival forest analysis of clinical factors and laboratory variables in older patients with various types of cancer, we showed that the CRP/albumin ratio made the largest contribution to the prediction of one-year mortality." (PMID 34944774, 2021). "The mechanism of CRP upregulation is controlled by proinflammatory cytokines from tumor cells or the immune system, which leads to repeated stimulation and chronic inflammation, forming a carcinogenic microenvironment that favors the development of cancer." (PMID 34221966, 2021). "This fact, along with the evolving understanding that pCRP can be converted into mCRP in situ, which is not, at present, easily quantified in aqueous blood samples, have limited interpretation of the meaning of CRP as an index of inflammation in cancer patients." (PMID 34552600, 2021). "Given our data, we hypothesize that low albumin and high LDH and CRP serve as markers of cancer-related systemic inflammation and cachexia, resulting also in a greater hypercoagulable state in these patients." (PMID 34521927, 2021). "However, to make a solid conclusion on the CRP prognostic value in CRC patients, future studies should be conducted with regard to the CRP relationship to overall and cancer-specific survival rates." (PMID 34441316, 2021).
cancer (continued). "Therefore, we conducted a secondary analysis of a prospective cohort study in palliative care units across Japan to investigate the relationships between serum levels of CRP and subtypes of pain in patients with advanced cancer cachexia." (PMID 34223511, 2021). "Similarly, high serum CRP and low serum albumin concentrations are prognostic markers for numerous cancers." (PMID 34962922, 2021). "The release of cytokines by cancer cells results in a rise in the serum CRP level at the same time." (PMID 33482792, 2021). "The prognostic value of CRP and albumin have been well established in a variety of cancers 15-18." (PMID 33758615, 2021). "In a study of advanced NSCLC patients treated with chemotherapy, n = 142 patients considered evaluable for cancer related CRP were suggested to have better prognosis if CRP levels decreased after two cycles of treatment, contrary to our findings for the docetaxel arm." (PMID 33534859, 2021). "Serum CRP and albumin levels are prognostic markers in multiple cancer types." (PMID 33434414, 2021). "CRP performed best in patients with advanced and CA 19-9 in patients with low cancer stages." (PMID 34572824, 2021). "Taken together, it was considered that lymphocyte-to-CRP score could reflect host cytotoxic-immune response to tumors, systemic inflammation, and nutritional status in patients with cancer." (PMID 33507925, 2021). "However, a previous study reported that the prevalence of CRP ≥ 1.0 mg/dL was 79.6% in patients with advanced cancer in palliative care settings." (PMID 33757453, 2021). "In particular, for carcinogenesis and cancer progression, C-reactive protein (CRP) and interleukin-6 (IL6) are key cancer-promoting inflammatory cytokines that are interrelated in oncogenesis and tumor growth through different molecular pathways in response to acute and chronic inflammation." (PMID 34572592, 2021). "A recent systematic review and meta-analysis has described a relationship between chronic inflammation, as measured by inflammatory circulating biomarkers (including C-reactive protein (CRP) and interleukin-6 (IL-6)) and an increased cancer incidence, including CRC." (PMID 35008324, 2021). "When patients with an underlying diagnosis of cancer were excluded from the analysis, combined biochemical markers of low-grade inflammation (GPS), serum CRP >10mg/L and low serum albumin concentrations <35 g/L remained independently associated with higher 6-month mortality." (PMID 34962922, 2021). "Indeed, although most of the cytokines are considered as biomarkers of cancer cachexia along with CRP, they need cautious validation." (PMID 33801569, 2021). "The downregulation of anti-cancer responses may be a key activator for the inflammatory pathways characterized by the elevated concentrations of CRP, which are important for the development of several malignancies." (PMID 34899835, 2021). "Although there have been many studies on cancers and inflammatory diseases with inflammatory cytokines, fibrinogen, CRP, albumin, and hematological indexes as inflammatory markers, these parameters are limited in the differential diagnosis of IGM and early onset BC." (PMID 34356979, 2021). "Further, MR can allow the assessment of a long-standing effect of CRP on cancer development." (PMID 33614510, 2020). "They showed that CRP was generally 1.3-fold higher than normal level in all cancer types." (PMID 33344503, 2020). "One reflective focus involves evaluating how CRP may affect the fibrinolytic-like responses that are recognized as hallmarks of cancer growth." (PMID 33324413, 2020). "Elevated levels of baseline C-reactive protein (CRP), a marker of systemic inflammation and immune activation, are associated with poor treatment response to chemotherapy and adverse disease outcome in various cancers including advanced NSCLC." (PMID 32824580, 2020). "A recent Swedish study assessed CRP and PA levels up to the death of 155 incurable cancer patients." (PMID 32209087, 2020).
cancer (continued). "On the other hands, cancer cells have been shown to express CRP and produce various cytokines." (PMID 33121520, 2020). "We aim to examine how added sugar and SSB intake associate with 136 measured plasma proteins and C-reactive protein (CRP) in the Malmö Diet and Cancer–Cardiovascular Cohort (n = 4382), and examine if the identified added sugar- and SSB-associated proteins associate with T2D incidence." (PMID 33066363, 2020). "Furthermore, laboratory results with respect to C-reactive protein and platelet count as well as the incidences of cancer-related deaths and new, worsening, or recurrent cancer were similar in the inclisiran and placebo groups in each trial." (PMID 33089390, 2020). "Our patients should be regarded as representative in their clinical (e.g., age, performance status, and survival), biological (e.g., tumor and cancer cell characteristics), and prognostic parameters (e.g., Leibovich score, tumor characteristics, and CRP level)." (PMID 32707675, 2020). "Recent studies have indicated that CRP-to-albumin ratio (CAR), also created on serum albumin levels and CRP levels, is a valuable prognosticator in various cancers and may provide more accurate prognostic prediction than other indicators." (PMID 32587804, 2020). "Potential SIR-related biomarkers in cancer patients include as CRP, NLR, PLR, albumin and GPS." (PMID 32974174, 2020). "One study found a positive correlation between CRP levels and cancer mortality, but only in males." (PMID 33243216, 2020). "Elevated levels of CRP are also observed in some cancer patients." (PMID 33291708, 2020). "In patients with cancer, CRP levels are well known to correlate with IL-6 levels." (PMID 33291708, 2020). "It is still a subject of debate whether CRP enhancement is derived from hepatocytes as a consequence of the inflammatory response or directly from malignant tumor cells." (PMID 31936329, 2020). "Although there is no clear evidence of the diagnostic or etiological role of CRP in cancer, several studies have reported higher levels of this protein in cancer patients than in healthy individuals." (PMID 32974174, 2020). "The interpretation of increased serum CRP levels in elderly cancer patients should therefore be careful because aging, frailty, and other disorders may all contribute to the increased CRP levels." (PMID 32707721, 2020). "However, previous studies have shown that aggressive cancer behavior produced a detrimental inflammatory response, which lead to elevated serum CRP level." (PMID 33351844, 2020). "CRP is one of the most frequently used serum markers to evaluate prognosis of cancer, but it lacks specificity and could be elevated in a number of systemic influences such as infections, surgery, and connective tissue disease." (PMID 32676164, 2020). "C-reactive protein (CRP), an acute-phase protein, is primarily synthesized by hepatocytes in response to systemic inflammation and has been demonstrated to represent a prognostic factor in various cancer entities including HNSCC." (PMID 32182693, 2020). "These medical conditions might also limit systemic or local treatment options in cancer patients with progressive recurrent disease after curative intent resection, and hereby CRP may also play an indirect role in poor cancer survival." (PMID 32423000, 2020). "In the present study, Alb and CRP were predictors in cancer patients, as in previous reports." (PMID 32438645, 2020). "Studies have shown that systemic inflammatory markers, including cytokines, C-reactive protein (CRP), albumin, serum amyloid A and leukocytes, may be independent prognostic factors in cancer patients." (PMID 32022510, 2020). "Level of CRP increases blood circulation in various immunologically mediated inflammatory conditions, including trauma, infection, surgery, burns, allergic reactions, and cancer." (PMID 32974174, 2020).
cancer (continued). "We also investigated whether CRP could affect the predictive potential of the apoB/apoA-I ratio for cancer mortality and vice versa." (PMID 31936330, 2020). "The Glasgow Prognostic Score (GPS) incorporates serum C-reactive protein and albumin levels and has been shown to be a reliable independent prognostic factor in pancreatic, colorectal, gastro-esophageal, hepatocellular and other malignant tumors." (PMID 33147766, 2020). "Alb and CRP are well known as predictors of prognosis in cancer patients." (PMID 32438645, 2020). "Hence, the detection of low-level CRP is an important task for the prognostic management of diseases like cancer, stress, metabolic disorders, cardiovascular diseases, and so on." (PMID 32213807, 2020). "In closing we discuss the possibility that therapeutic lowering of baseline CRP might be a useful way to treat certain diseases, including cancer." (PMID 33633738, 2020). "Furthermore, this is the first study that evaluated the predictive value of both apoB/apoA-I ratio and CRP levels in relation to cancer mortality." (PMID 31936330, 2020). "Several mechanisms for the elevation of the CRP level in cancer patients have been proposed." (PMID 33059654, 2020). "In survival analyses, cancer-specific prognostic impact was found for CRP, IL6, and IL1RA." (PMID 33066437, 2020). "Further evaluation of the role of CRP in cancer will undoubtably improve its ability as a biomarker to indicate disease severity and progression more precisely, and thus may reveal it as an indispensable asset in clinical decision making." (PMID 33324413, 2020). "Pre- and postoperative serum levels of a panel of three inflammatory biomarkers YKL-40, IL-6, and CRP with the two cancer biomarkers CEA and CA19-9 showed that the patients with 2 or more elevated biomarkers had shorter RFS and OS after resection of liver metastases." (PMID 32756596, 2020). "Previous studies have suggested that CRP elevation might not only be derived from an increased production in hepatocytes as a response to cancer-related systemic inflammation, but could also represent a result of CRP production in malignant cells themselves." (PMID 32182693, 2020). "Cancer is mainly a disease of the elderly; for the elderly cancer patients, increased CRP levels may not only reflect their malignant disease, but may also be a part of the (normal) aging process." (PMID 32707721, 2020). "Additionally, elevations in ferritin, high-sensitivity C-reactive protein, erythrocyte sedimentation rate, procalcitonin, prothrombin time, interleukin-2 (IL-2) receptor, and interleukin-6 (IL-6) were observed in cancer patients." (PMID 32522278, 2020). "After controlling for measures of socioeconomic position, we found associations between CRP and cancer mortality in the NHANES III sample, but we found non-significant trends in the NHANES 1999–2002 sample." (PMID 33243216, 2020). "Multiple studies have demonstrated the predictive value of CRP in cancer outcomes." (PMID 33344503, 2020). "The lack of a significant association between rs3091244 and cancer risk suggests that circulating CRP does not play a causal role in tumorigenesis." (PMID 32477370, 2020). "We find evidence that only in one unique stratum is earlier life CRP, and not fibrinogen, associated with prospective cancer mortality." (PMID 33243216, 2020). "Since inflammation is recognized as a critical component of tumor progression, CRP could be a predictor of cancer mortality." (PMID 31936330, 2020). "During a median follow-up of 37 days, the following cancer patient characteristics were found to be positively associated with COVID-19 death: Asian ethnicity, palliative treatment, initial cancer diagnosis >24 months, dyspnea at presentation, and high CRP levels." (PMID 32903324, 2020). "However, the median cutoff value of CRP/Alb ratio reported in one meta-analysis for the subject of several cancers was 0.095." (PMID 32856868, 2020).